RTL5 (retrotransposon Gag like 5)
Synonyms: KIAA2001; RGAG4; Mar5; Mart5; SIRH8; 6430402L03Rik
Tractability: No criterion of Open Targets' tractability assessment is met for any kind of drug.
Gene: Protein-coding gene on chromosome X (72,127,110 to 72,131,915, reverse strand). Ensembl gene ENSG00000242732.
Subcellular location (Human Protein Atlas): Nucleoplasm
Homologues: Orthologues: chimpanzee RTL5 (99% identical), macaque RTL5 (96% identical), pig RTL5 (80% identical), guinea pig RTL5 (77% identical), mouse Rtl5 (70% identical), rat Rtl5 (70% identical), rabbit RTL5 (69% identical). Paralogues in human: RTL1 (18% identical), PEG10 (18% identical), RTL3 (17% identical), RTL6 (12% identical), RTL10 (9% identical), LDOC1 (8% identical), RTL4 (8% identical), RTL8A (6% identical), RTL8B (6% identical), RTL8C (6% identical).
Diseases named in the same sentence as RTL5 in open-access papers:
RTL5 is named in the same sentence as 4 diseases in open-access papers, as found by Europe PMC text mining. Sharing a sentence is not in itself a finding about the gene and the disease. The quoted sentences say what the papers report.
viral infection (1 paper, 2022). "In addition, it will be important to evaluate the acute and chronic effects of LPS, dsRNA and non-methylated DNA administration, and/or viral infection in the Rtl5 KO and Rtl6 KO mice using other less invasive methods to assess their biological significance in vivo." (PMID 36162816, 2022).
RTL5 also shares sentences with these, for which no sentence is quoted: bacterial infection (1 paper); fungal infection (1); infection (1).